CD36 (CD36 molecule (CD36 blood group))
Diseases named in the same sentence as CD36 in open-access papers (continued):
Sharing a sentence is not in itself a finding about the gene and the disease.
cervical cancer (29 papers, 2019 to 2025). A primary or metastatic malignant neoplasm involving the cervix. "More specifically, treatment of cervical cancer cells with TGF-β increased CD36 expression and exhibited a significant loss in the expression of E-cadherin." (PMID 35008415, 2022). "Having uncovered a close association between CD36 and invasion of cervical cancer cells, we sought to elucidate the effect of CD36 on the EMT in these cells." (PMID 31655604, 2019). "Alterations in CD36 expression may be associated with high-risk human papillomavirus infection and may promote the development and progression of cervical cancer." (PMID 37795297, 2023). "CD36 was exclusively linked to uterine prolapse, uterine cervicitis, and uterine cervical diseases, while the other biomarkers were associated with conditions such as uterine hemorrhage, uterine anomalies, uterine cervical dysplasia, uterine neoplasms, and uterine cervical neoplasms." (PMID 39640883, 2024). "Cervix cancer cases reported 59% cases gained CD36 copy number, 95% cases gained CD47 copy number, and 58% of cases lost TSP-1 copy number." (PMID 39627379, 2024). "RNA-Seq analysis revealed that overexpression of the HPV16/18 E6/E7 genes upregulated GP6, CD36, HDAC6, ESPL1, and DNMT3B among the differentially expressed genes (DEGs) associated with cervical cancer." (PMID 39411320, 2024). "Consistence with our finding, there is report that CD36 can promote the growth of cervical cancer by activating Src and ERK signaling pathways." (PMID 37612265, 2023). "Disruption of CD36 in oleic acid-induced HeLa cells as well as mice models significantly inhibited cervical cancer carcinogenesis by downregulating the Src/ERK pathway in vitro and in vivo." (PMID 37686324, 2023). "Their results indicated that OA promotes metastasis and growth of cervical cancer by inducing CD36-dependent activation of Src kinase and downstream of the ERK1/2 pathway." (PMID 36428985, 2022). "The correlation of CD36 and miR-1254 with cervical cancer development was re-confirmed by co-transfection of miR-1254 mimic and CD36 overexpression using CCK-8, colony formation, transwell and western blot assays." (PMID 36008842, 2022). "Oleic acid had been reported to enhance cervical cancer cell growth by regulating CD36 expression and promoting cancer cell migration and proliferation." (PMID 36557318, 2022). "Increased expression of CD36 rescued the effects of miR-1254 upregulation on cervical cancer progression, suggesting that miR-1254 suppresses cervical cancer development by modulating CD36." (PMID 36008842, 2022). "In advanced cervical cancer, CD36 expression is correlated with poor tumor differentiation, EMT markers expression, and positive lymph node metastasis." (PMID 36568966, 2022). "Further experiments proved that dietary OA upregulated CD36 expression which promotes tumour growth and metastasis in cervical cancer cells HeLa." (PMID 36428985, 2022). "The transwell assays showed that upregulation of CD36 rescued the promotive effects of miR-1254 on cervical cancer cell invasion." (PMID 36008842, 2022). "CD36 overexpression reversed the inhibitory effects of upregulated miR-1254 in the cervical cancer cells, suggesting that miR-1254 regulates cervical cancer progression by modulating CD36." (PMID 36008842, 2022). "We constructed miR-1254 and CD36 co-overexpressing cervical cancer cells and performed CCK-8, colony formation, and transwell experiments." (PMID 36008842, 2022). "We constructed miR-1254 and CD36 co-overexpressing SiHa and CaSki cervical cancer cells using miR-1254 mimic and pIRES2-ZsGreen1-CD36." (PMID 36008842, 2022). "Subsequently, the CCK-8 and colony formation assays showed that the proliferative ability of the cervical cancer cells was significantly enhanced after the expression of CD36 increased." (PMID 36008842, 2022). "miR-1254 attenuated the invasion and proliferation of cervical cancer cells by modulating the expression levels of CD36." (PMID 36008842, 2022).
cervical cancer (continued). "In agreement, forced CD36 overexpression in cervical cancer cells promotes proliferation and enhances cell migration and invasion." (PMID 36568966, 2022). "The analyses showed that increased CD36 overexpression reversed the suppressive effects of miR-1254 mimic on cervical cancer cell proliferation and invasion compared with miR-1254 mimic alone." (PMID 36008842, 2022). "Studies showed that OA induced the activation of Src kinase and its downstream ERK1/2 via a CD36-dependent manner to promote cervical cancer cell growth and metastasis." (PMID 34434893, 2021). "Consistent with this, overexpression studies have shown CD36 to increase the migration and invasion of cervical cancer cells in vitro, and its knockdown inhibited their metastatic potential." (PMID 34215227, 2021). "Our early work showed that dietary oleic acid (18 : 1)-induced CD36 promotes cervical cancer cell growth and metastasis." (PMID 33771982, 2021). "In ovarian and cervical cancer, it was observed that CD36, as Lox-1, leads to cancer progression and metastasis." (PMID 34063116, 2021). "Our previous work has also demonstrated that upregulation of Src pathway by CD36 is a potential mechanism to induce cervical cancer cell growth and metastasis." (PMID 33771982, 2021). "Published studies present a range of CD36 expression, from 19% in squamous cell carcinoma of the esophagus to 70% in cervical carcinoma." (PMID 34439279, 2021). "Using immunohistochemistry, we analyzed 133 cervical cancer samples for CD36 protein expression levels, and then investigated the correlation between changes in its expression and clinicopathologic parameters." (PMID 31655604, 2019). "In vitro invasion and in vivo metastasis assays were also used to evaluate the role of CD36 in cervical cancer metastasis." (PMID 31655604, 2019). "CD36 immunoreactivity was detected in 73.68% (98/133) of cervical cancer cases, whereas CD36 was only expressed in 19.15% (9/47) of normal cervical tissues." (PMID 31655604, 2019). "In summary, our results reveal a close link between CD36 expression and the progression of cervical cancer." (PMID 31655604, 2019). "Our findings suggest that CD36 is likely to be an effective target for guiding individualized clinical therapy of cervical cancer." (PMID 31655604, 2019). "SiHa- and HeLa cells-transfected CD36 siRNA-2 were used to ascertain the effects of CD36 on migration and invasion of cervical cancer cells by trans-well and wound-healing assays." (PMID 31655604, 2019). "In the present study, we confirmed that CD36 was highly expressed in cervical cancer samples relative to normal cervical tissues." (PMID 31655604, 2019). "To further investigate the effects of CD36 on a series of biologic processes in cervical cancer cell lines, we used Western blotting analysis to detect the expression of CD36 in C33a, Hce1, HeLa, and SiHa cells." (PMID 31655604, 2019). "In the present study, we aimed to demonstrate that CD36 acts as a novel carcinogenic factor in TGF-β-mediated EMT in cervical cancer." (PMID 31655604, 2019). "We postulate that after validation in large clinical cohorts, CD36 will be an effective target for guiding individualized clinical therapy of cervical cancer." (PMID 31655604, 2019). "The effect of CD36 expression on the epithelial–mesenchymal transition (EMT) in cervical cancer cells was evaluated by Western immunoblotting analysis." (PMID 31655604, 2019). "Colony formation assays and flow cytometry were used to examine the proliferative and apoptotic effects of CD36 in cervical cancer cell lines." (PMID 31655604, 2019). "In this study, we revealed that CD36 immunoreactivity in cervical cancer tissues is significantly higher than that in normal tissues." (PMID 31655604, 2019). "Our results presents the first clinical study showing a significant correlation between high CD36 expression and poor overall survival of cervical cancer patients." (PMID 31655604, 2019).
cervical cancer (continued). "After investigating the expression levels of CD36 in 133 cases of cervical cancer tissues and 47 cases of normal cervical tissues by immunohistochemistry, we found CD36 expression to be primarily located on the cell membrane or in the cytoplasm." (PMID 31655604, 2019). "Oleic acid also promotes cervical cancer progression by up-regulating CD36 expression." (PMID 35130983, 2022). "These lines of evidence suggest that CD36 may be a potential therapeutic target for the treatment of various cancers, including cervical cancer." (PMID 36008842, 2022). "CD36 is expressed in human cervical cancer cell lines (C33a, Hce1, HeLa and SiHa cell lines)." (PMID 36568966, 2022). "Furthermore, CD36 has been shown to promote EMT in cervical cancer through interactions with the TGF-β pathway." (PMID 35008415, 2022). "Meanwhile, in cervical cancer cells CD36 has been shown to promote EMT by interacting with TGF-β." (PMID 33232276, 2020). "There are currently few reports on the expression and actions of CD36 in cervical cancer." (PMID 31655604, 2019). "Therefore, our evidence verified a vital role for CD36 in the promotion of cervical cancer cell migration and invasion in vitro." (PMID 31655604, 2019). "Collectively, our data suggest that CD36 participates in the EMT in cervical cancer." (PMID 31655604, 2019). "Moreover, we demonstrated that CD36 facilitated invasion and metastasis of cervical cancer cells, and this constituted a possible mechanism by which CD36 promoted EMT." (PMID 31655604, 2019). "In addition, using Kaplan–Meier survival analysis and TCGA datasets, we showed that patients with cervical cancer and high CD36 expression levels had an unfavorable prognosis relative to those with low or medium CD36 expression (P = 0.02)." (PMID 31655604, 2019). "However, there are few reports regarding the roles of CD36 in initiation and metastasis of cervical cancer." (PMID 31655604, 2019). "Moreover, overexpression of CD36 promoted invasiveness and metastasis of cervical cancer cells in vitro and in vivo, while CD36 knockdown suppressed proliferation, migration, and invasiveness." (PMID 31655604, 2019). "Thus, investigation of a new molecular mechanism for CD36 in cervical cancer metastasis is critical in improving patient prognosis." (PMID 31655604, 2019). "Therefore, miR-1254 exerts anti-tumour effects in cervical cancer by modulating CD36 expression." (PMID 36008842, 2022). "Through cross-screening of HPV infection-related DEGs and cervical cancer-related DEGs, we identified five significantly upregulated DEGs, e.g., GP6, CD36, HDAC6, ESPL1, and DNMT3B." (PMID 39411320, 2024). "By acting synergistically with TGF-β, CD36 enhances EMT and promotes metastasis in cervical cancer cells." (PMID 36008842, 2022). "Thus, we wondered whether miR-1254 could affect CD36 expression in cervical cancer cells." (PMID 36008842, 2022). "Treatment of cervical cancer cells with TGF-β, a classic EMT inducer, promotes CD36 expression, indicating a link between EMT activation and CD36 expression." (PMID 36568966, 2022). "Oleic acid elevates the membrane expression of CD36, a FA transporter, and induces Srs kinase, activating the downstream ERK1/2 pathway to promote cervical cancer cell proliferation and invasion in a CD36-dependent manner." (PMID 34666780, 2021). "Various genes, namely GLS, CD36, WNT5a, HRAS, DDB2, PIK3R2, and CDH2 were found to be differentially highly expressed in primary cervical cancer samples of patients who developed distant recurrence." (PMID 35087740, 2021). "Oleic acid induces CD36 via SRC/ERK activation, which contributes to cervical cancer formation and the progression of cervical cancer." (PMID 34959830, 2021). "More importantly, CD36 promoted the EMT process at least partially via the TGF-β signaling pathway, thus contributing to the progression of cervical cancer." (PMID 31655604, 2019).
cervical cancer (continued). "To further validate CD36 promotion of cervical cancer metastasis by regulating EMT, we attempted to detect the effect of CD36 on some critical EMT markers." (PMID 31655604, 2019). "The pathway analysis revealed the correlation between CD36 and the PI3K/AKT/mTOR signaling pathway, which is consistent with previous research and further strengthens the potential role of CD36 in HPV infection and cervical cancer." (PMID 37795297, 2023). "Furthermore, CD36 has been shown to promote cell growth and metastasis as well as epithelial-to-mesenchymal transition (EMT) in cervical cancer." (PMID 35008415, 2022). "Therefore, we herein suggest that CD36 and TGF-β interact with each other to promote EMT in cervical cancer." (PMID 31655604, 2019). "Hence, targeting CD36, RhoE, FAD104, p68, or SIX alongside TGF-β signalling inhibition could be new therapeutic avenues for cervical cancer treatment." (PMID 36766756, 2023). "It is notable that CD36 has negative staining in 35 cervical cancer samples." (PMID 31655604, 2019). "Namely, GLS, CD36, WNT5a, HRAS, DDB2, PIK3R2, and CDH2 were significantly DE between cervical cancer without recurrence and cervical cancer with distant recurrence." (PMID 35087740, 2021).
colorectal cancer (29 papers, 2014 to 2025). A primary or metastatic malignant neoplasm that affects the colon or rectum. "In the case of studying colorectal cancer, overexpression of CD36 is associated with a significant increase in invasion and metastasis." (PMID 36428985, 2022). "The link between colorectal cancer risk and CD36 has been explored in that variants in rs1984112 have been associated with hypercholesterolemia, a known risk factor colorectal cancer." (PMID 33926505, 2021). "Overall, in colorectal cancer, cancer cells can increase fatty acid uptake by upregulating the expression of FATPs, CD36, and FABPs, thereby maintaining the rapid proliferation and growth of tumors." (PMID 40718481, 2025). "on inducing colorectal cancer cell death through AAV–CD36 knockdown, we explored the potential of targeting CD36 in TNBC therapy." (PMID 41267927, 2025). "For example, in colorectal cancer, CD36 promoted GPC4 ubiquitination via proteasome-dependent pathway and exerts inhibitory effects on glycolysis through the β-catenin-c-MYC signaling pathway." (PMID 40083702, 2025). "For example, the FASN inhibitor TVB-3664 has shown significant anti-cancer activity in colorectal cancer models, an effect correlated with the upregulation of CD36, suggesting a compensatory mechanism involving increased fatty acid uptake." (PMID 41212437, 2025). "We have previously shown that CD36, a transporter of fatty acid, promotes colorectal cancer tumor growth." (PMID 35008415, 2022). "Here, in studying the role of CD36 in colorectal cancer, we found that CD36 promotes colorectal cancer invasion in vitro and metastasis in vivo and that overexpression of CD36 upregulates expression of the matrix metalloproteinase MMP28." (PMID 35008415, 2022). "Based on these findings, it seems likely that CD36 promotes colorectal cancer metastasis by upregulating MMP28 and E-cadherin cleavages." (PMID 36428985, 2022). "We previously found that colorectal cancer (CRC) cells with a higher metastatic potential express a higher level of fatty acid translocase (CD36)." (PMID 35008415, 2022). "In colorectal cancer, a progressive decrease in CD36 expression reportedly leads to tumour progression from adenomas to carcinoma, with CD36 loss enhancing prognosis." (PMID 34561446, 2021). "Accordingly, a very recent report demonstrated that inhibition of FASN upregulated the lipid receptor CD36 and stimulated the uptake of a lipophilic fluorochrome in colorectal cancer cells." (PMID 33928023, 2021). "Colorectal cancer surgical patients showed increased NK cell lipid content, higher CD36 expression, decreased granzyme B and perforin production in addition to reduced cytotoxicity in the postoperative period." (PMID 31429730, 2019). "Here, the authors address CD36 function in colorectal cancer and show it acts as a tumour suppressor by inhibiting B-catenin/myc signalling, resulting in downregulation of glycolysis." (PMID 31484922, 2019). "While phylogroup I is decreased in CD, UC, and colorectal cancer, depletion of phylogroup II was specifically related to CD36." (PMID 28904372, 2017). "In another case, the patient with colorectal cancer developed methylprednisolone-induced thrombocytopenia after the oxaliplatin-induced thrombocytopenia, attributable to the oxaliplatin immune-induced syndrome owing to anti-GPIIbIIIa and anti-CD36 antibodies." (PMID 38903494, 2024). "Knowledge about the role CD36 in adenoma development may provide greater insight into the development of colorectal cancer." (PMID 33926505, 2021). "Conversely, CD36 acts as a tumor suppressor and inhibits aerobic glycolysis by promoting GPC4 ubiquitination and inhibiting β‐catenin/c‐myc signaling in colorectal cancer." (PMID 41267927, 2025). "For instance, in colorectal cancer PLIN2 promotes macrophage polarization towards the M2 phenotype and activates the CD36-dependent epithelial-mesenchymal transition (EMT) pathway in colorectal cancer cells, thereby enhancing tumor invasiveness." (PMID 41246346, 2025).
colorectal cancer (continued). "In previous studies, we demonstrated upregulation of FABP4 and CD36 in SARFIFA-positive gastric and colorectal cancers by investigating spatial and bulk RNA-data as well as immunohistochemical protein expression." (PMID 38216952, 2024). "It was found that the biomarkers of efferocytosis (AXL, CD36, UCP2) and macrophage repair indicators SPMs (RvD1, RvE1, LipoxinA4) were significantly increased in animal models and postoperative colorectal cancer patients." (PMID 36691021, 2023). "The reprogramming of lipid metabolism has been highlighted in colorectal cancer (CRC) studies, suggesting a critical role for the scavenger receptor CD36 and fatty acid synthase (FASN) in this malignancy." (PMID 36556492, 2022). "However, the roles of CD36 in colorectal cancer (CRC) remain unknown." (PMID 31484922, 2019). "Accordingly, genetic knock-down of FASN upregulated CD36 and lipid uptake in colorectal cancer, but not in OC cells." (PMID 33928023, 2021). "Furthermore, human colorectal cancer tissues treated with TVB-3664 show a significant and selective upregulation of CD36 mRNA." (PMID 32850342, 2020). "Interestingly, despite these similarities, treated OC cells, unlike colorectal cancer cells, showed neither CD36 upregulation nor activation of lipid uptake." (PMID 33928023, 2021). "The upregulation of CD36 and lipid uptake represents a long-term compensatory response to the treatment that can be induced in colorectal carcinoma cells but not in OC cells, since in the latter, the cell damage induced by the treatment is too severe to allow activation of relief pathways." (PMID 33928023, 2021).